CDK4 (cyclin dependent kinase 4)
Diseases named in the same sentence as CDK4 in open-access papers (continued):
Sharing a sentence is not in itself a finding about the gene and the disease.
melanoma (continued). "As another example, the preclinical observation that CDK4/6 inhibition can attenuate NRAS oncogenic signaling when combined with MEK inhibition has led to an undergoing clinical investigation of the synergistic inhibition of CDK4/6 (PD-0332991) and MEK1/2 (selumetinib) in NRAS-mutant melanomas." (PMID 34123788, 2021). "Multiple clinical trials evaluated CDK4/6 inhibitors as single agent regimen or in combination with BRAF ± MEK inhibitors as first or subsequent line of therapy in patients with advanced solid tumors, including melanoma." (PMID 34071228, 2021). "S6K1 inhibition may resensitize NRAS-mutant melanoma carrying PIK3CA E545K to combined MEK and CDK4/6 inhibition." (PMID 34804979, 2021). "EdU, transwell, and wound healing assays were conducted to verify whether CDK4 or VWF inactivation can affect the proliferation, migration, and invasion of melanoma cells." (PMID 34582363, 2021). "Although CDK4/6 inhibition has no substantial effect on the metabolic phenotype following BRAF/MEK targeted therapy in melanoma, CDK4/6 inhibition alone significantly enhances mitochondrial metabolism." (PMID 33572972, 2021). "Together, these data suggest that CDK4/6 activity does not alter glycolysis in BRAF mutant melanoma cells, nor does it effect the glycolytic response following MAPK pathway inhibition." (PMID 33572972, 2021). "The CDK4 inhibitor PD0332992 has been analyzed by the FDB for the treatment of cancer and is in early clinical trials for a variety of solid tumors, including melanoma." (PMID 34422248, 2021). "Beyond the cell cycle, CDK4/6 regulates cell metabolism, which is a critical factor determining response to standard-of-care mitogen-activated protein kinase (MAPK) pathway therapies in melanoma." (PMID 33572972, 2021). "In melanoma cells with or without BRAFV600E inhibitor resistance, inhibiting the expression of CDK2, CDK4, KIT, and VWF may become a new choice to inhibit the progression of melanoma." (PMID 34582363, 2021). "In addition, oncogenic markers typical of basal cell carcinoma (Gli-1, Gli-2, Ptch-1, n = 2 cases) and melanoma (c-kit, MAGE, CDK4, n = 1) were markedly upregulated in skin lesions." (PMID 33509032, 2021). "Cyclin-dependent kinases CDK4 and CDK6 represent promising therapeutic targets in human melanoma." (PMID 34485433, 2021). "Indeed, previous studies showed the synergistic antitumoral effects of a combination of CDK4/6 inhibitors and MEK inhibitors in neuroblastoma, colorectal cancer, non-small cell lung cancer, and melanoma." (PMID 33807122, 2021). "Superficial spreading melanoma can also arise within small nevi, which were not visible at birth, usually after puberty, and can reveal a cancer predisposition syndrome (CDKN2A or CDK4 germline mutations)." (PMID 34449585, 2021). "Finally, blockage of CDK4/CDK6 kinases, which were part of the resistance program, inhibited melanoma cells growth in vitro and in vivo in a melanoma mouse model." (PMID 33535416, 2021). "In the GSE32474 dataset, the expression levels of CDK2, CDK4, KIT, and VWF in the melanoma metastasis group were significantly higher than those in the melanoma primary focus group (t = 2.616, 2.244, 2.137, and 2.570, respectively; logFC = 1.206, 0.240, 1.573, and 0.168, respectively; p < 0.05)." (PMID 34582363, 2021). "Overall our findings indicate the BRAF-MEK-CDK4/6i can be employed in combination with ACT and provides additional evidence that supports clinical studies of CDK4/6i in combination with BRAF-MEKi in advanced melanoma." (PMID 34944961, 2021). "In addition, the balanced expression of CDK4 and CDK6 is crucial to allow CDK6 to act as transcriptional regulator as has been shown in melanoma cells." (PMID 33255177, 2020). "This cyclin-dependent kinase 4/6 (CDK4/6)-dependent signature was detected prior to immunotherapy and predicted clinical responses to anti-PD-1 therapy in an independent cohort of 112 patients with melanoma." (PMID 33268350, 2020).
melanoma (continued). "In line with this, we found gene amplifications of MDM2 and MDM4 in 26% and of CDK4/6 in 13% of the melanoma biopsies of patients that did not respond to ICB." (PMID 32165639, 2020). "Another study reported that the T cell exclusion signature was predictive of poor ICB response, however, CDK4 and CDK6 inhibitors could reverse this signature to get a better response in in vitro experiments in melanoma." (PMID 32091408, 2020). "Among these kinases, 6 (RPS6KB2, DSTYK, TBRG4, CDK4, POLR2E, FASTKD5) and 4 (STK26, PAK1, EPHB2 and JAK3) were consistently up- or down-regulated, respectively, in the metastatic lines of at least two pairs of melanoma cells." (PMID 32051510, 2020). "Alterations of the CDK4/6 signaling pathway is observed in different types of melanoma, concomitantly with NRAS, KRAS or BRAF; thus the genetic profiling of CDK4/6 may provide insights for the targeted treatment of various types of melanoma." (PMID 33233603, 2020). "Our studies revealed that KYN inhibited the protein level of cyclin D1 and CDK4 in melanoma A375 cells, but not in more resistant RPMI7951 cells." (PMID 33114713, 2020). "Eight patients, with true features of hereditary melanoma such as MPM and high number of nevi which were negative for germline mutations in CDKN2A, CDK4, and MITF (p.E318K) genes were selected for WES." (PMID 32276436, 2020). "In this work, we employed whole exome sequencing (WES) to identify novel susceptibility genes for hereditary melanoma in patients with MPM, who were negative for germline mutations in the genes CDKN2A, CDK4, and MITF (p.E318K)." (PMID 32276436, 2020). "One mouse model system that established CDK4 as a melanoma oncogene used a knock-in of CDK4, which alone was not sufficient to induce tumorigenesis, but required carcinogen challenge before the phenotype was revealed." (PMID 31342168, 2019). "In summary our data point at a role for CDK4 and CDK6 in controlling angiogenesis in melanoma." (PMID 30858922, 2019). "To further test whether CDK4 and CDK6 knockdown reduces secretion of pro-angiogenic factors we examined the effect of supernatant secreted by melanoma cells on the proliferation of human endothelial cells (HUVECs)." (PMID 30858922, 2019). "To validate this finding we employed a xenotransplantation model with the human melanoma cell line 518A2 (expressing wildtype CDK4 and p16INK4a, data not shown)." (PMID 30858922, 2019). "Genomic profiling of 23 available subjects also identified gene amplifications of cell cycle regulators (Cyclin D1, CDK4, or CDK6), fibroblast growth factors (FGF19, FGF3, and FGF4) and EMSY (a DNA repair inactivating gene) uniquely clustered in acral melanoma subjects in the study." (PMID 30642373, 2019). "To rule out this possibility, we treated NRAS-mutant melanoma cells with a cdk4/6 inhibitor to induce cell cycle arrest and assessed TERT levels." (PMID 29695835, 2018). "This variant co-segregated with cancer in a family with 14 melanoma cases who were not carriers of germline mutations in the two known melanoma genes, CDKN2A and CDK4." (PMID 30453575, 2018). "Currently the only established high penetrance familial melanoma genes are CDKN2A and CDK4." (PMID 29523635, 2018). "In the present study, OL decreased the HFD-induced expression of CDK4/cyclin D1, inhibited HFD-induced reduction of apoptotic cell numbers, and inhibited the HFD-induced decreases in the levels of cleaved PARP in B16F10 melanoma tumor tissues." (PMID 28410190, 2017). "Inhibition of Rb phosphorylation in melanocytes and melanoma cells, either by addition of chemical CDK4 inhibitors or RNAi-mediated knockdown of CDK4, did not mimic the effects of p16 loss." (PMID 28915557, 2017). "One class includes specific CDK4/6 inhibitors (such as palbociclib, ribociclib, and abemaciclib), which are being used in cancers that retain Rb-pathway functionality and/or amplification of CDK4 or CDK6, such as ER-positive breast cancers, melanomas, and sarcomas." (PMID 28107181, 2017).
melanoma (continued). "We initially focused the analysis to on variants in genes known to cause familial malignant melanoma, but we did not identify any clearly causative variation in these genes (BAP1, CDK4, CDKN2A, MC1R, MITF and PTEN)." (PMID 28623311, 2017). "We surveyed kinome expression patterns across sub-populations of the BRAF/NRAS wild type sample and found that CDK4 and CDK2 were consistently highly expressed in the majority of cells, suggesting that these kinases might be involved in melanoma progression." (PMID 27903987, 2017). "Altogether, above results indicate that abrogating Rxrα expression in the epidermis in combination with activated CDK4 and N-RAS contributes to enhanced proliferation, malignant conversion, and vascularization of melanomas, and exposure to a single neonatal dose of UVB accelerates this process." (PMID 29121869, 2017). "The patient has no reported family history of melanoma and is not carrier of the high-risk genes CDKN2A and CDK4." (PMID 27022491, 2016). "Moreover, the suppression of cyclin D1 and cyclin E by CoQ0 led to the inhibition of CDK4 and CDK2 levels in melanoma cells." (PMID 26968952, 2016). "In this study, we found that hSulf-1 overexpression in melanoma cells can inhibit cell proliferation and induce cell cycle arrest and apoptosis by decreasing the protein kinase B (AKT) phosphorylation and limiting CDK4 nuclear import." (PMID 27806323, 2016). "The “melanoma pathway” ranked in the top 5, where we found three sub-pathways that were enriched with DM genes, DE genes, or target genes of DE miRNAs (Ras/Raf/MEK/ERK, PI3K/AKT, and CDK4/6/Rb)." (PMID 25537510, 2015). "Further evaluation of CDK4 protein levels in a larger panel of cell lines, and ultimately in tumour samples from melanoma patients treated with PD0332991, would be required to definitively determine the clinical relevance of CDK4 protein as a predictive biomarker for PD0332991 response." (PMID 26201960, 2015). "CDK4, a cell cycle G1/S kinase, and cyclin D1 (CCND1), were shown to be amplified in melanoma." (PMID 24743024, 2014). "Identification of two high-risk MC1R variants in our identical twins in the absence of CDKN2A and CDK4 mutations highlights the contribution of low penetrance genes, such as MC1R, in melanoma susceptibility." (PMID 22978401, 2012). "In one study of melanomas arising at chronic sun damaged sites CDK4 and CCND1 were implicated as independent oncogenes in melanomas without mutations in BRAF or N-RAS." (PMID 25562798, 2012). "Moreover, CDK4 and CDK6 have been proved to be overexpressed in cutaneous melanoma, which suggests a possible role in melanoma development." (PMID 22419847, 2012). "In conclusion, in the majority of Ashkenazi Jewish families with an inherited predisposition to melanoma with or without NST, CDKN2A/ARF and CDK4 loci are unlikely to be implicated in the predisposition to melanoma and the associated neural system tumours." (PMID 15928671, 2005). "Taken together with the data reported herein, it appears that in over 60 Ashkenazi Jewish melanoma families, no germline alteration in CDKN2A/ARF and CDK4 loci underlie the apparent predisposition." (PMID 15928671, 2005). "Four germline alterations have been described in Cdk4 to date, in four melanoma-prone kindreds and in one melanoma patient with no known family history." (PMID 14735200, 2004). "In this study, we evaluated the effectiveness of the CDK4/6 inhibitor, palbociclib, the CDK2 inhibitor, PF-07104091, the dual CXCR1 and CXCR2 (CXCR1/2) antagonist, SX-682, and the combination of these inhibitors for effective treatment of melanoma in preclinical models." (PMID 40904502, 2025).
melanoma (continued). "Although no preclinical studies in melanoma have been published to date evaluating the efficacy of a pan-CDK2/4/6 inhibitor or the combination of a CDK4/6 inhibitor with a CDK2 inhibitor, studies have explored the impact of CDK2 inhibition on melanoma growth control." (PMID 40282469, 2025). "Some of them have been tested in melanoma, e.g., CDK4, but without clinical success so far." (PMID 39340537, 2024). "However, we found that a higher percentage of melanoma cells (1.1–7.1%) developed persisters and entered the S phase within 3 days of CDK4/6 inhibition compared to non-transformed cells (0–1.5%)." (PMID 38030655, 2023). "Interestingly, we found that FAK exhibited increased activity and cytoplasmic localization, which was correlated with increased CDK4 expression, in human melanoma compared with same-patient normal skin controls." (PMID 35525274, 2022). "Notably, for melanomas with NRAS mutations, inhibition of MEK alone is not sufficient to completely inhibit the activation of downstream signaling mediated by NRAS through CDK4." (PMID 36125617, 2022). "Investigation of novel therapeutic approaches involving combinations of several anti-melanoma agents (such as dual targeting of BRAF/MEK and cyclin-dependent kinases CDK4/6) could provide significant improvement in the prognosis of BRAF-mutated metastatic melanoma patients." (PMID 36613518, 2022). "However, melanoma lesions showed elevated cytoplasmic-active FAK and increased CDK4 expression." (PMID 35525274, 2022). "Taken together, the cell cycle arrest in the two human melanoma cell lines SK-MEL-28 and WM115 is either mediated indirectly by the induction of p21, which inhibits various CDKs, as in the case of cytokines and doxorubicin, or directly by the synthetic CDK4/6 inhibitor palbociclib." (PMID 35563820, 2022). "Furthermore, we did not observe changes of MHC Class I expression in several human melanoma cell lines which indicates the response to CDK4/6i is not universal." (PMID 34944961, 2021). "As a first step in order to understand if the selected E2F target genes could function as predictor markers of CDK4/6 inhibition resistance, we compared the expression profiles of E2F1, CDC6, DHFR, H2AFZ, MCM2, and ATAD2 among the four canine melanoma cell lines." (PMID 34485433, 2021). "Cyclin dependent kinase 4/6 inhibitors (CDK4/6i) may also play a role in enhancing duration of response in combination with BRAF-MEKi via blockade of the cell cycle and exerting immunomodulatory effects on melanoma." (PMID 34944961, 2021). "The high frequency of CDK4/6 pathway activation in cancer more broadly has led to the development of CDK4/6 inhibitors, such as palbociclib, ribociclib and abemaciclib, and the therapeutic effects of palbociclib have been studied in the context of BRAF inhibitor resistance in melanoma." (PMID 33572972, 2021). "To investigate whether CDK4/6 inhibition alone or in combination with BRAF and MEK inhibition alters metabolic pathways in melanoma, we utilised the BRAF mutant melanoma cell lines WM266.4 and A375 and specific inhibitors of CDK4/6 (palbociclib), BRAF (vemurafenib), and MEK (cobimetinib)." (PMID 33572972, 2021). "However, only one or no mutation was identified in the melanoma-susceptibility genes like CDKN2A and CDK4." (PMID 32083130, 2020). "Confirmatory molecular investigations for specific neoplasms are important for the use of targeted therapies such as BRAF or CDK4 inhibitors (in confirming that patients have melanoma rather than CCS and for patients with DDL, respectively) and for patient enrolment into appropriate clinical trials." (PMID 33061792, 2020).
melanoma (continued). "Interestingly, KYNA in the highest tested concentration (5 mM) decreased CDK4 protein level and phosphorylation of Rb in A375 cells, despite no significant changes in proliferation (DNA synthesis) of KYNA-treated A375 melanoma cells." (PMID 33114713, 2020). "Importantly tumor nodules completely regressed thereafter and were no longer visible or palpable 9 days after injection of melanoma cells that had either decreased CDK4 or CDK6 expression in contrast to the controls which rapidly increased in volume." (PMID 30858922, 2019). "CDK4 alleles did not segregate with melanoma in a reference population, and lastly an association analysis showed that MITF could not be related to melanoma occurrence in the MeLiM model." (PMID 29963229, 2018). "Therefore, monotherapy with CDK4/6 inhibitors is not considered an effective treatment modality in melanoma." (PMID 29371923, 2017). "As Denmark is a high incidence country for melanoma, there is a distinct possibility of phenocopies in families, and since only one person from each family was examined for CDKN2A and CDK4 mutations, it cannot be ruled out that mutations in some families have not been identified." (PMID 25803691, 2015). "However, CGH analysis of our panel of seven melanoma cell lines did not reveal amplifications in cyclin D1 or CDK4 (data not shown)." (PMID 17245336, 2007). "Amplification of the other two genes may not be important in the tumorigenesis of melanomas, as only one CDK4 and no CCND1 amplification was observed." (PMID 8611425, 1996). "In addition, an open label, phase Ib clinical trial is examining naporafenib (LXH254, a RAF inhibitor) in combination with either LTT462 (an ERK1/2 inhibitor), trametinib, or ribociclib (a CDK4/6 inhibitor) in NRAS or BRAFV600 mutant melanoma and non-small cell lung cancer." (PMID 35954441, 2022). "Detection of two high-risk MC1R variants in our identical twins in the absence of CDKN2A and CDK4 mutations highlights the contribution of low penetrance genes, such as MC1R, in melanoma susceptibility, although additional known or as yet unknown genetic risk factors might be involved." (PMID 22978401, 2012). "A few melanoma‐prone families, with no linkage to CDKN2A, have been found to carry PVs in CDK4, thus having alterations affecting the same cellular mechanism as CDKN2A, since p16INK4a is a direct inhibitor of CDK4 function." (PMID 40072281, 2025). "WGS studies have suggested that TWT melanomas, commonly of the AM subtype, are more likely to have focal amplifications of CCND1, MDM2, KIT, and KRAS, as well as CDK4 and CDK6, than non-TWT melanomas." (PMID 39858514, 2025). "In this study, we demonstrate that although CDK4/6 inhibition does not potentiate the metabolic effects of BRAF and MEK inhibition in melanoma, there is a significant upregulation of mitochondrial activity following CDK4/6 inhibition." (PMID 33572972, 2021). "Our analyses have revealed that inhibition of CDK4/6 upregulates glutamine and fatty acid-oxidation-dependent mitochondrial metabolism in BRAF mutant melanoma cells, but they do not alter glycolysis nor the metabolic response to MAPK inhibitors." (PMID 33572972, 2021). "Without CDK4/6 inhibitor treatment, in CMM12 cells H2AFZ and MCM2 appeared to be more highly expressed compared to the other melanoma cell lines." (PMID 34485433, 2021).